CRP (C-reactive protein)
Diseases named in the same sentence as CRP in open-access papers (continued):
Sharing a sentence is not in itself a finding about the gene and the disease.
Sepsis (continued). "Additionally, the dual measurement index of the LAR is superior to traditional indicators, such as C-reactive protein and procalcitonin, which are single-factor indicators that cannot reflect metabolic disturbances in patients with sepsis." (PMID 40046181, 2025). "LPS-induced sepsis is well known to disrupt hematopoiesis and trigger systemic inflammation through the activation of innate immune pathways, leading to alterations in RBCs indices, WBCs profiles, and acute-phase reactants such as C-reactive protein (CRP)." (PMID 40871061, 2025). "Furthermore, the SROC curves for RETN and CRP in predicting sepsis in neonates and children indicated high predictive abilities, with AUC values of 0.925 and 0.945, respectively." (PMID 40416430, 2025). "Therefore, this study aims to comprehensively evaluate the diagnostic value of multiple biomarkers, including presepsin, PCT, and CRP, for sepsis detection in severe burn patients." (PMID 40868016, 2025). "In addition, 9.8% (2/20) of the cases had clinical and biochemical evidence of sepsis, indicated by elevated C-reactive protein levels." (PMID 40951023, 2025). "Additionally, elevated NT-proBNP and troponin levels suggested cardiac strain, while a sudden rise in CRP was attributed to an Extended-Spectrum Beta-Lactamase-producing (ESBL) Escherichia coli septicaemia." (PMID 40698215, 2025). "The sensitivity analyses with altered criteria for organ failure and infection showed similar AUCs of calprotectin and CRP (AUC 0.59–0.61 for calprotectin and AUC 0.68–0.73 for CRP) to distinguish sepsis from non-sepsis, compared to the operational sepsis criteria used in the main analyses." (PMID 40319081, 2025). "CRP is an acute-phase protein produced by the liver in response to inflammation and the elevated levels detected, compared with the literature, were consistent with sepsis prior to death." (PMID 39797963, 2025). "The 22 metabolic features, characterized by fewerfeatures butsuperior performance, were selected as a panel for septic shock prediction.For comparison, clinical features collected upon admission, includingtraditional sepsis biomarkers like CRP, PCT, lactate, and WBC, werealso used for modeling." (PMID 40340384, 2025). "The CRP levels were often high in cases of sepsis and digestive diseases that may comprise a number of infectious and inflammatory diseases, and the optimal cut-off level for CRP was slightly higher." (PMID 40005032, 2025). "Compared to static values that may reflect temporary inflammation (such as transient elevation of CRP after trauma), trend analysis can help distinguish between true sepsis progression and acute phase reactions." (PMID 40661134, 2025). "This variability could influence observed inflammatory states, as CRP levels fluctuate dynamically during sepsis progression." (PMID 40703270, 2025). "PC was positively correlated with the absolute monocyte count (R = 0.33, P = 0.0088) and monocyte percentage (R = 0.37, P = 0.0035) in sepsis patients, and negatively correlated with commonly used clinical inflammatory markers CRP (R=-0.48, P = 1e-04) and PCT (R=-0.36, P = 0.0056)." (PMID 41346598, 2025). "In this study, CRP levels were significantly higher in non-survivors compared to survivors, suggesting a potential association with sepsis-related mortality." (PMID 40310418, 2025). "The development of AKI in sepsis patients was strongly associated with RDW, APACHE II score, and the biomarkers PCT, IL-6, CRP, and cystatin C. After the intervention, the incidence of AKI and AKI grade 3 significantly decreased, along with lower rates of renal replacement therapy and mortality." (PMID 41281283, 2025). "The combined use of SAA proteins with other biomarkers, such as C-reactive protein (CRP) and procalcitonin (PCT), enhances diagnostic accuracy for early detection of sepsis, particularly in cases involving severe trauma or infections like urinary tract infections." (PMID 40061939, 2025).
Sepsis (continued). "CRP and procalcitonin are effective sepsis markers in neonates." (PMID 40915180, 2025). "Also, when the presence of bacteremia was included as an additional criterion, the PCT and CRP combination reached a sensitivity of 90% and the specificity of 80% with considerably high AUC at 0.88 for prediction of sepsis." (PMID 41011807, 2025). "This CRP cut-off makes it easier to include high-inflammation diseases, such as sepsis." (PMID 40005032, 2025). "In dogs with nSIRS and sepsis, median CRP concentration progressively decreased over time." (PMID 40607352, 2025). "A prospective cohort study suggested that sTREM-1 levels in patients with sepsis admitted to the ICUs could reflect infectious conditions more accurately than CRP and PCT levels." (PMID 41225969, 2025). "•False-positive rate of CRP in sepsis diagnosis reaches about 44 %." (PMID 41429071, 2025). "We further tested the impact of CRP deficiency on the clearance of K. pneumoniae, an important Gram-negative pathogen of hospital-acquired pneumonia and sepsis with over 100 capsule types." (PMID 41214213, 2025). "Notably, a recent study explored a prognostic advantage of combining PCTc with blood parameters, such as white cell count, platelet count and CRP, for predicting mortality in cancer patients with sepsis." (PMID 41357484, 2025). "Vitamin C supplementation in sepsis patients led to significant improvements over 12 months, with reductions in IL-6 (345.16 ± 128.52 to 245.12 ± 83.78 pg/mL), C-reactive protein (CRP) (175.31 ± 62.43 to 114.57 ± 38.67 mg/L), and malondialdehyde (MDA) levels (8.94 ± 3.21 to 5.79 ± 2.18 nmol/mL)." (PMID 40296930, 2025). "However, a newer systematic review found that CRP levels ≥ 60 mg/L show promising discriminatory ability for sepsis in neonates in low- and middle-income settings (AUC 0.87, 95% CI 0.76 to 0.91)." (PMID 39825283, 2025). "Compared to infants never receiving antibiotics, CRP was markedly higher in infants treated with antibiotics, especially in infants fulfilling sepsis diagnostic criteria." (PMID 41441318, 2025). "Several studies have demonstrated that aptamer-based biosensors match or exceed antibody-based systems in sensitivity, often reaching femtomolar or even attomolar detection limits for sepsis-related biomarkers, such as IL-6, CRP, and tumor necrosis factor-alpha (TNF-α)." (PMID 40710052, 2025). "Current evidence suggests integrating CRP with other markers to optimize diagnostic accuracy rather than employing it as a standalone tool for sepsis screening." (PMID 40895306, 2025). "Conversely, at the same point in time, an NLR around 4, or less, along with a statistically significant and consistent decrease in fibrinogen, CRP, or procalcitonin, could represent elements that predict patient survival after a sepsis episode." (PMID 41153844, 2025). "Antibiotics were administered due to raised CRP and suspected sepsis." (PMID 40948504, 2025). "In recent years, cfDNA and CRP have gained attention as potential biomarkers for assessing sepsis." (PMID 40282303, 2025). "However, despite its routine clinical use, the prognostic value of CRP in predicting sepsis outcomes remains controversial." (PMID 40310418, 2025). "•Prognostic value of CRP for mortality in sepsis remains uncertain." (PMID 41429071, 2025). "Moreover, the included studies emphasized the benefit of utilizing CRP in conjunction with other sepsis biomarkers to increase the accuracy of EOS and LOS diagnosis." (PMID 40970024, 2025). "Anaphylaxis is a severe systemic hypersensitivity reaction that can present with overlapping clinical and laboratory features of sepsis, including fever, tachycardia, hypotension, and elevated inflammatory markers such as C-reactive protein (CRP) and white blood cell (WBC) count." (PMID 39941456, 2025). "Additionally, there was a significant correlation between maternal and neonatal vitamin D status and C-reactive protein, as well as all markers of sepsis in the blood count." (PMID 40150674, 2025).
Sepsis (continued). "CRP in infants diagnosed with sepsis was especially high at 36 h." (PMID 41441318, 2025). "The authors suspect that, for instance, a rise in CRP following a tangential necrectomy may mimic early sepsis, potentially prompting an unnecessary pharmacological intervention." (PMID 40507966, 2025). "Furthermore, the diagnostic value of CRP (AUC 0.469–0.558) and PCT (AUC 0.535–0.654) with regard to blood-culture positive sepsis was poor during the first week of ICU hospitalization." (PMID 37204560, 2024). "The early detection of sepsis in diabetic individuals with UTI may be achieved using a comprehensive analysis of CRP, WBC, and ALB test findings." (PMID 38771840, 2024). "However, the only usage of PCT had the AUC over 0.8, suggesting that it was a powerful indicator for recognizing sepsis compared to CRP." (PMID 38771840, 2024). "Additionally, C-reactive protein, serum lactate, and L/A ratio were significantly higher among patients with septic shock than in patients with sepsis." (PMID 38576552, 2024). "Notably, the diagnostic performance of CRP and PCT, as evidenced by their respective AUCs of 0.78 and 0.82, confirms that PCT is slightly more reliable than CRP in diagnosing sepsis, a finding that has been consistently reported in recent studies." (PMID 39469363, 2024). "Furthermore, single-cell RNA sequencing identifies upregulation of amphiregulin in leukocyte populations during sepsis, which we validate as a plasma analyte that correlates with clinical signs of disease, even when C-reactive protein is normal." (PMID 38195661, 2024). "PLAC8 in total granulocytes rivals CRP as a blood biomarker of sepsis." (PMID 39434093, 2024). "In cases of trauma, surgery, and autoimmune diseases, elevated CRP levels do not necessarily suggest the presence of sepsis, as the elevation is often associated with sterile inflammation." (PMID 39201697, 2024). "This lack of specificity limits the utility of CRP as a standalone diagnostic tool in sepsis, highlighting the need for additional markers to enhance diagnostic accuracy." (PMID 39469363, 2024). "In addition, IL-6 has been shown to be a better diagnostic marker for sepsis compared to PCT and CRP." (PMID 39589972, 2024). "Our findings indicated that CRP, with a cutoff value of 65.95, showed a sensitivity of 81.75% and a specificity of 84.6%, with an AUC of 0.832, indicating a significant positive correlation in predicting sepsis." (PMID 39776743, 2024). "Contrarily, the C-reactive protein/albumin ratio and qPitt bacteremia score are two relatively simple to use, widely available, and readily obtained severity scores in patients with sepsis." (PMID 39252713, 2024). "Monitoring body temperature, WBC count, and CRP daily can aid in early diagnosis of sepsis." (PMID 38580989, 2024). "CRP is a well-established marker of systemic inflammation, and several studies have demonstrated similar correlations, particularly in conditions such as sepsis and cardiovascular diseases, where oxidative stress plays a crucial role." (PMID 39598124, 2024). "Several mortality-relevant biomarkers have been identified in patients with sepsis, and these markers represent a promising avenue for improving sepsis management, such as C-reactive protein, procalcitonin, presepsin, protein C, monocyte chemo-attractant protein-1, and angiotensin." (PMID 39294760, 2024). "MDSCs, CRP, and PCT showed higher diagnostic values for sepsis than LDNs, M-MDSCs, and PMN-MDSCs." (PMID 38609858, 2024). "Further, levels of CRP could indicate sepsis approximately two days before the appearance of clinical symptoms." (PMID 39716257, 2024). "The exact mechanism by which sepsis and septic shock lead to the onset or unmasking of atrial fibrillation is not fully understood, but studies have shown an increase in C-reactive protein before the onset of atrial fibrillation, indicating a close relationship between inflammation, sepsis, and AF." (PMID 39336476, 2024).
Sepsis (continued). "Numerous studies had confirmed the clinical significance of CRP in the early diagnosis of sepsis." (PMID 39347502, 2024). "However, CRP lacks specificity for sepsis and can be elevated in other inflammatory conditions, thus limiting its diagnostic usefulness for sepsis." (PMID 39130839, 2024). "In the present study, CRP is markedly higher in neonates with sepsis than in the control group." (PMID 38907854, 2024). "Notably, procalcitonin (PCT) and C-reactive protein (CRP) have been extensively considered biomarkers for the diagnosis and prognosis of sepsis." (PMID 38534604, 2024). "Therefore, in this prospective observational study, we aimed to analyze these parameters (available from CBC and CRP) for the prediction of sepsis and outcomes in the ICU." (PMID 39776743, 2024). "Similarly, the production of PCT is increased in response to sepsis, and it rises within 2–3 h of infection and gains a peak at 24 h, which is a much quicker rise than CRP (which reaches a peak at 72 h)." (PMID 38247605, 2024). "Recent studies suggest that P-SEP may be used as a more accurate biomarker in neonatal sepsis than CRP and PCT." (PMID 38535886, 2024). "Together, our data provides insight into early-life sepsis-induced dysregulation and highlights a panel of immune analytes, which could be combined with current laboratory tests including CRP, to rule-out sepsis with greater accuracy." (PMID 38195661, 2024). "While CRP may offer some predictive value for sepsis, PCT is a more promising biomarker for sepsis prediction and early identification." (PMID 39130839, 2024). "Among the biomarkers assessed in this study, C-reactive protein levels were higher in patients with septic shock compared to sepsis (sepsis, median = 14.0 mg/L, IQR, 8–22, range, 0.5–614; septic shock, median = 24.0 mg/L, IQR, 15–38.85, range, 2.3–200; mean rank difference = −123.19, p = 0.001)." (PMID 38576552, 2024). "Furthermore, the sepsis patient’s biomarker concentrations exceed 100 mg L−1 and 10 ng mL−1 for C-reactive protein and procalcitonin, respectively." (PMID 38920613, 2024). "However, there is evidence supporting CRP as a prognostic indicator and early predictor of sepsis in burn patients." (PMID 39716257, 2024). "Interestingly, similar findings were observed in a study of 57 pediatric burn patients wherein a rise in serum CRP predicted sepsis 82% of the time, with 100% sensitivity as sepsis was always preceded or accompanied by a rise in serum CRP levels." (PMID 39716257, 2024). "In a study of sepsis, both C reactive protein and procalcitonin levels were higher among the AA homozygotes compared with the G‐allele carriers, indicating that a significantly stronger pro‐inflammatory response among AA patients compared with G‐allele carriers." (PMID 38629742, 2024). "For instance, only 66.7% had CRP values, which is one of the most valuable preoperative markers for identifying sepsis as a complication of SP, while others like procalcitonin were not recorded, partly due to the high cost of the test and limited access for many patients." (PMID 39347224, 2024). "Therefore, the study found that nCD64 had higher sensitivity and specificity compared to traditional sepsis markers such as CRP and TLC, potentially offering a faster and more accurate diagnostic tool for clinicians." (PMID 39429998, 2024). "However, the AUC for sepsis of our multivariate model was significantly higher than the AUCs of both CRP and PCT (Bonferroni’s correction, both p < 0.001)." (PMID 38337856, 2024). "Additionally, empiric sepsis evaluation and antibiotic use are unnecessary since infants with gastroschisis often exhibit elevated C-reactive protein and an elevated immature-to-total neutrophil ratio." (PMID 39311328, 2024). "However, infection-specific transcriptional pathways, that differentiate sepsis from sterile stress-induced granulocytosis more reliably than CRP, remain to be identified." (PMID 39434093, 2024).
Sepsis (continued). "C-reactive protein (CRP) is a well-studied marker in neonates and is used as a biomarker in sepsis." (PMID 38698211, 2024). "While levels of C-reactive protein (CRP) as an established sepsis marker were similarly able to predict the need for mechanical ventilation in patients with septic shock and high SOFA score, CRP levels were not able to discriminate survivors from non-survivors." (PMID 39524325, 2024). "We identified core cellular and plasma immune traits that dynamically correlated with sepsis episodes and moreover, could differentiate babies with sepsis that presented with low CRP." (PMID 38195661, 2024). "The most sensitive biomarkers for predicting sepsis were CRP (81.75%) and MDW (81.7%)." (PMID 39776743, 2024). "Notably, presepsin is less susceptible to noninfectious inflammatory conditions such as trauma, burns, and surgery than other conventional sepsis markers such as procalcitonin and C-reactive protein (CRP)." (PMID 39091978, 2024). "In both the 30-patient qRT-PCR subcohort used to analyze the total granulocytes as well as in the 25-patient qRT-PCR subcohort used for the HD and LD granulocytes, fully contained in the first qRT-PCR subcohort, only higher mean CRP values in sepsis than SIRS were statistically significant." (PMID 39434093, 2024). "The aim of this study was to assess the CD64 biomarker expression on neutrophils using the flow cytometry method and its comparison with total leukocyte count, C-reactive protein (CRP) level, and blood culture sensitivity test in the diagnosis of sepsis in adults." (PMID 39429998, 2024). "Furthermore, correlation between Cp and other acute phase proteins (C-reactive protein, α-1-antitripsin, α-2-macroglobulin, and alkaline phosphatase) is observed in sepsis." (PMID 38008825, 2024). "Our data intriguingly demonstrate, as a proof-of-concept, that immune analytes might serve as adjuncts to standard laboratory measures including CRP, to aid clinicians to rule-out sepsis with greater accuracy." (PMID 38195661, 2024). "Both studies reflect that CRP can potentially be used in the correct clinical context of sepsis." (PMID 38698211, 2024). "Moreover, when sepsis is suspected, a total of 89.7% measure circulating blood leucocytes; 92.3% use CRP; 84.6% measure PCT; and 100% measure lactate." (PMID 38337815, 2024). "CRP levels significantly increased at 24 h and 48 h post-sepsis induction." (PMID 39459616, 2024). "In particular, prognostic biomarkers derived from the pathophysiology of sepsis may help guide treatment and monitoring of the disease, the most widely studied ones being C-reactive protein (CRP) and procalcitonin (PCT)." (PMID 38430552, 2024). "Despite their common use in sepsis diagnosis, both CRP and PCT have their own shortcomings." (PMID 39416748, 2024). "In our case, there was increased CRP and leukocytosis which could be related to hyperinflammation as a result of HS and coexisting sepsis." (PMID 39229360, 2024). "Recent studies have been questioning the role of WBC and CRP in sepsis." (PMID 38256033, 2024). "In order of importance, APACHE II, mean platelet volume (MPV), eosinophil counts (EoC), and C-reactive protein (CRP) showed higher importance for predicting sepsis patient survival, whereas, SOFA, APACHE II, platelet counts (PLTC), and CRP obtained higher importance in the SIRS cohort." (PMID 38489347, 2024). "While significantly higher levels of procalcitonin and CRP were recorded in sepsis caused by Gram-negative and Gram-positive bacteria when compared to the control group." (PMID 39417064, 2024). "Additionally, C-reactive protein, serum lactate, and the L/A ratio were significantly elevated in patients with septic shock compared to those with sepsis." (PMID 38576552, 2024).